RNU7-107P (RNA, U7 small nuclear 107 pseudogene)
Gene: Small nuclear RNA gene on chromosome 10 (50,590,652 to 50,590,712, reverse strand). Ensembl gene ENSG00000238523.
Homologues: Orthologues: chimpanzee U7 (100% identical), macaque U7 (95% identical). Paralogues in human: RNU7-120P (82% identical), RNU7-1 (80% identical), RNU7-113P (80% identical), RNU7-167P (80% identical), RNU7-18P (80% identical), RNU7-35P (80% identical), RNU7-37P (80% identical), RNU7-65P (80% identical), RNU7-73P (80% identical), RNU7-75P (80% identical), RNU7-7P (80% identical), RNU7-81P (80% identical), and 142 more.